USP22 (ubiquitin specific peptidase 22)
Diseases named in the same sentence as USP22 in open-access papers (continued):
Sharing a sentence is not in itself a finding about the gene and the disease.
liver cancer (13 papers, 2018 to 2025). An epithelial or non-epithelial malignant neoplasm that arises from the liver. "USP22 showed high expression levels and frequent alterations in liver cancer, which was strongly linked to a dismal prognosis for these cancer patients." (PMID 38638430, 2024). "Its targets span a wide spectrum, from the USP22-Wnt/β-catenin pathway in liver cancer cells to MAPK1 in cervical cancer cells." (PMID 38370338, 2024). "USP22 stimulates the growth and incidence of tumours and is significantly expressed in several malignancies, including breast, colorectal and liver cancers." (PMID 39661501, 2024). "To define the specific role of USP22 in HCC, we first analyzed the Cancer Cell Line Encyclopedia and revealed the ninth highest expression of USP22 in liver cancer cells among 1,457 human cancer cell lines from 40 tumor types." (PMID 35449157, 2022). "The genetic removal of USP22 led to the suppression of liver cancer growth, boosted tumor immunogenicity and the presence of tumor-infiltrating lymphocytes, and heightened the effectiveness of therapies targeting PD-L1 and CDDP-based chemotherapy in mouse models." (PMID 38638430, 2024). "In addition, another study in our group revealed that ubiquitin-specific protease 22 (USP22) can deubiquitinate PD-L1 to stabilize the protein, leading to liver cancer immune resistance." (PMID 36539510, 2023). "Noncoding RNAs can play an important role in liver cancer by regulating USP22." (PMID 35935969, 2022). "In addition to affecting the drug resistance of liver cancer cells, USP22 can also regulate peroxisome proliferator-activated receptor γ (PPARγ) in HCC through deubiquitination to promote fatty acid synthesis and tumorigenesis." (PMID 35875077, 2022). "In addition, lncRNA HULC downregulates the expression of microRNAs that target directly the 3′-UTR of USP22 (miR-6825-5p, miR-6845-5p, and miR-6886-3p) in liver cancer cells and prevents by this inhibition of USP22 at translational level." (PMID 29967761, 2018). "In addition to the effect on drug resistance of liver cancer cells, other studies have also reported that USP22 can significantly affect the glycolysis and stemness characteristics of liver cancer cells under hypoxic conditions: HIF-1α knockdown inhibits USP22-induced and hypoxia-induced effects." (PMID 35875077, 2022). "USP22, USP14, USP10, USP13, USP7, USP2, and USP8, liver cancer-related DUBs, have also been reported to have related small molecule inhibitors, but the research and development are not mature enough." (PMID 35875077, 2022). "In addition, USP22 stabilises HIF‐1α through deubiquitination, and its expression promotes hypoxia and stem cell induced glycolysis in liver cancer cells." (PMID 39661501, 2024). "In addition, USP22 can also be regulated by lncRNA HULC to further affect the drug resistance and tumor growth of liver cancer cells." (PMID 35875077, 2022).
lung carcinoma (13 papers, 2017 to 2026). "USP22 is frequently overexpressed in lung cancer and associated with poor prognosis of lung cancer patients." (PMID 37946202, 2023). "Low USP22 gene expression is associated with better prognosis in lung cancer patients according to KM poltter database." (PMID 32665011, 2020). "Importantly, we observe that all anti–PD-1 responding patients with lung cancer show statistically significant lower USP22 expression levels, which are reversibly associated with increased tumoral HLA-I (β2M) expression and CD8+ T cell infiltration." (PMID 41252204, 2025). "Importantly, USP22 upregulation was associated with ICB immunotherapeutic resistance in patients with lung cancer." (PMID 41252204, 2025). "USP22 was early identified as a member of an 11-gene “death-from-cancer” signature that is strongly associated with disease recurrence, metastasis, and treatment failure in a wide range of cancer types, including lung cancer." (PMID 37946202, 2023). "We recently showed that USP22 may be associated with cisplatin resistance in lung cancer stem cell through downregulation of ALDH1A3." (PMID 31842906, 2019). "Interestingly, an earlier study identified that USP22 is one of an 11-gene transcriptional signature which was associated with aggressive growth, metastasis, and therapy resistance in a number of human cancers including lung cancer." (PMID 31842906, 2019). "Another in vitro study using non‐small cell lung cancer demonstrated the importance of USP22 in the malignancy of lung cancer." (PMID 41541703, 2026). "In lung cancer, the transcription factors AP2A and AP2B were found to promote the expression of the USP22 gene, which is associated with aggressive growth and therapy resistance." (PMID 39869563, 2025). "We found that the addition of 0.5, 2.5 μM of FT671 significantly elevated USP22 luciferase reporter activity and 1.25 μM FT671 induced a dynamic increase of USP22 mRNA level in both A549 and H1299 lung cancer cells." (PMID 37946202, 2023). "We found that FT671 only slightly suppressed the parental cancer cell proliferation and significantly suppressed the proliferation of USP22-Ko lung cancer cells." (PMID 37946202, 2023). "We found that the USP7-specific inhibitor FT671 dramatically upregulates USP22 protein in a dose-dependent manner, even at a very low concentration that barely affects cellular proliferation in lung cancer cell line A549." (PMID 37946202, 2023). "Consistent with the potential oncogenic role of USP22 in lung cancer, AP2 also appears to play a positive role in tumorigenesis." (PMID 36123698, 2022). "In this study, we found that AP2, ATF3, c-Myc, NF-YA, and SP1 are critical to USP22 mRNA expression in lung cancer cells." (PMID 36123698, 2022). "Spearman correlation analysis demonstrated a moderate correlation between AP2 TFs and USP22 (r = 0.32, p < 0.001), suggesting that USP22 overexpression in lung cancer tissues is partially due to increased prevalence of the AP2 TF family." (PMID 36123698, 2022). "Elevated USP22 in lung cancer predicts highly malignant clinical behavior and is associated with poorer overall survival." (PMID 35935969, 2022). "Our findings indicate AP2α and AP2β are important transcription factors driving USP22 gene expression to promote the progression of NSCLC, and further support USP22 as a potential biomarker and therapeutic target for lung cancer." (PMID 36123698, 2022). "Based on this analysis, multiple truncated fragments of the USP22 gene promoter were amplified from genomic DNA of human lung cancer cell H1299 to construct various promoter region-driven luciferase reporter plasmids." (PMID 36123698, 2022). "EMT is considered to be a core mechanism of invasion and metastasis in various cancers, and overexpression of USP22 is able to regulate EMT to promote tumor progression in lung cancer." (PMID 35935969, 2022). "USP22 has been proposed as a putative cancer stem cell marker and a novel drug target in cancers including lung cancer." (PMID 31842906, 2019).
lung carcinoma (continued). "Although overexpression of USP22 has been observed in various cancers including lung cancer, our understanding of potential roles of USP22 in NSCLC is still largely incomplete." (PMID 31842906, 2019). "In lung cancer, USP22 was reported to be correlated with advanced differentiation and stage, poor prognosis of NSCLC cancer." (PMID 31842906, 2019). "USP22 can promote lung cancer cell invasion via epithelial-mesenchymal transition (EMT), which participates in the metastasis of primary tumors by activating TGF-β1." (PMID 28427243, 2017). "In addition, USP22 knockout drastically suppresses CSCs maintenance, in vivo angiogenesis, growth, and metastasis of lung cancer, and significantly sensitizes lung cancer cells including CSCs to cisplatin and irradiation." (PMID 37946202, 2023). "We previously showed that USP22-Ko significantly suppressed lung cancer xenograft growth." (PMID 37946202, 2023). "To test this hypothesis, we first examined if knockdown of USP7 will further suppress USP22-Ko lung cancer cell in vitro proliferation." (PMID 37946202, 2023). "Given the important roles of both USP22 and AP2 in lung cancer carcinogenesis, our finding of the association between these two proteins further supports USP22 deubiquitinate as a potential biomarker and therapeutic target for lung cancer." (PMID 36123698, 2022). "Moreover, immunohistochemical analysis shows that there is a positive correlation between AP2 TF and USP22 in lung cancer tissues, consistent with the oncogenic role of USP22 in lung cancer." (PMID 36123698, 2022). "In addition, we found that c-Myc, which can be stabilized through deubiquitination by USP22, upregulates USP22 at both transcriptional and post transcriptional levels, suggesting existence of a positive feedback loop between USP22 and c-Myc in lung cancer." (PMID 36123698, 2022). "USP22 inhibition restores cisplatin sensitivity in cisplatin-resistant lung cancer cells." (PMID 35935969, 2022). "The overexpression of USP22 resulted in the resistance of lung cancer cells to cisplatin." (PMID 35935969, 2022). "In conclusion, USP22 plays an oncogenic role in lung cancer and may be an important target for the carcinogenesis and drug resistance mechanism of NSCLC." (PMID 35935969, 2022). "We previously showed that cisplatin upregulates USP22 protein in lung cancer stem cells, indicating that activation of DNA-damage-repair pathways may potentially promote USP22 protein through either translational or post translational mechanisms." (PMID 36123698, 2022). "Downregulation of USP22 significantly impairs lung cancer stemness and resistance to cisplatin." (PMID 35935969, 2022). "Interestingly, migration and invasion assays also demonstrated that overexpression of AP2 significantly enhanced cellular migration and invasion potential in the USP22-WT H1299 and A549 cancer cells, but had little effect on migration and invasion in the USP22-KO lung cancer cells." (PMID 36123698, 2022). "We further tested another two USP7 inhibitors, HBX41108 and P5091, in the lung cancer cell H1299 and colon cancer cell HCT116, and found that both inhibitors dramatically upregulate USP22 in H1299 and HCT116." (PMID 37946202, 2023). "To further validate the specificity of the upregulation, we made siRNA-mediated USP7-knockdown (USP7-Kd) in A549 and H1299 lung cancer cells and found that USP7-Kd also markedly upregulates USP22 in both cancer cell lines." (PMID 37946202, 2023).
lung carcinoma (continued). "TCGA analysis showed a similar negative association of USP22 expression with CD8 scores in breast, prostate, and lung cancer." (PMID 41252204, 2025). "While our data demonstrate a strong negative correlation between USP22 and β2M across multiple human cancer types, we were only able to recruit 32 patients with lung cancer to assess the predictive value of USP22 expression for anti–PD-1 ICB responsiveness." (PMID 41252204, 2025). "We also analyzed mRNA expression in TCGA data and found there was a moderate correlation between USP22 mRNA expression with both AP2A and AP2Β expression in human lung cancer tissues, indicating AP2 may enhance USP22 transcription in lung cancer tissues." (PMID 36123698, 2022). "Finally, among lncRNAs, the intergenic LINC01426 was reported to promote the progression and stemness of lung cancer, an interaction with a member of the histone deubiquitinating complex Spt-Ada-Gcn5 acetyltransferase (SAGA), ubiquitin specific peptidase 22 (USP22), being suggested." (PMID 35873564, 2022). "In addition, consistent with our findings in breast, prostate, and colon cancers, tumoral USP22 and EZH2 protein expressions exhibited a strong positive correlation, and both were inversely correlated with tumoral β2M expression and with CD8+ T lymphocytes infiltration in lung cancer." (PMID 41252204, 2025). "Therefore, our results suggest that USP22 expression levels alone or combined with HLA-I expression levels and CD8+ T cell infiltration frequency prior to ICB, could serve as a more accurate biomarker to predict the ICB immunotherapeutic response for lung cancer treatment." (PMID 41252204, 2025).
prostate carcinoma (13 papers, 2016 to 2025). A carcinoma that arises from epithelial cells of the prostate gland. "Ki67 expression was associated with USP22 overexpression in cervical cancer, prostate cancer and oral squamous cell carcinoma." (PMID 27057639, 2016). "Overexpression of Usp22 was initially correlated with increased tumor growth, metastatic risk, and death from cancer in transcriptomic studies investigating the role of factors that regulate stemness in prostate cancer." (PMID 34503086, 2021). "This USP22-mediated activation can bypass androgens or AR antagonists (enzalutamide) to induce castration resistance in prostate cancer." (PMID 35935969, 2022). "In prostate cancer, USP22 predicts disease outcome and promotes the CRPC phenotype by controlling AR and MYC dual regulation." (PMID 35935969, 2022). "In prostate cancer, it has been reported that USP22 drives carcinogenic effects by regulating cell proliferation and DNA repair." (PMID 34548474, 2021). "USP22 promoted cancer progression by regulating cell proliferation and DNA repair in prostate cancer." (PMID 34753387, 2021). "Relationships between transcription factors and DUBs can be complex: for example USP7, USP12, USP14, USP22 all appear to regulate the stability and function of androgen receptor (AR) in prostate cancer." (PMID 30854565, 2019). "In prostate cancer cells, upon ligand binding, USP22 is recruited (and also promotes AR recruitment) to the promoter regions of AR- dependent genes such as KLK2, KLK3/PSA, TMPRSS2 and FKBP5." (PMID 27057639, 2016). "Importantly, CRISPR deletion of Usp22 led to a nearly complete rejection of syngeneic RM1 prostate cancer in immunocompetent C57BL/6J mice." (PMID 41252204, 2025). "In addition to RM1 prostate cancer, we confirmed that Usp22 inhibition impeded the growth of both orthotopic 4T1 TNBC and MC38 syngeneic tumors." (PMID 41252204, 2025). "Notably, a recent ubiquitinome-wide analysis identified the heat shock 70 kDa protein 5 (HSPA5, also known as BiP or GRP78) as a target of USP22-mediated deubiquitination in prostate cancer cells." (PMID 34007022, 2021). "In fact, the regulation of AR expression and function by USP22 in prostate cancer has been reported, but whether AR-V7 could be regulated by USP22 is elusive." (PMID 34548474, 2021). "Therefore it is possible that RNF6 and USP22 contribute to prostate cancer progression by changing AR activity and stability." (PMID 27057639, 2016). "In prostate cancer, USP22 overexpression lead to increased androgen receptor splicing." (PMID 27057639, 2016). "In the presence of USP22, AR protein levels are increased in prostate cancer cell lines." (PMID 27057639, 2016). "Usp22 inhibition resulted in a similar increase in HLA-ABC and β2M expression in both human prostate cancer PC3 and triple negative breast cancer (TNBC) MDA-MB-231 cells." (PMID 41252204, 2025). "Further, we observed that Usp22 targeted inhibition synergized with anti–PD-1 treatment leading to a complete rejection of orthotopic 4T1 TNBC, MC38 colon cancer and RM1 prostate cancer." (PMID 41252204, 2025). "USP22 impact on proliferation is further indicated by connections between USP22, the androgen receptor and c-MYC in prostate cancer cells and models." (PMID 38236941, 2024). "In prostate cancer, USP14, USP22, and USP26 were reported to play roles in cancer progression." (PMID 34545063, 2021). "Although USP22 was identified almost 15 years earlier as an important oncogenic driver for therapy resistant prostate cancer, not much work has been carried out to understand its importance in the development of mCRPC." (PMID 34660907, 2020). "Interestingly, the regulation of UPR by USP22 might not be limited to the HER2+-BC subtype, as an enrichment of UPR-specific gene signatures was also observed in mRNA-seq datasets of normal immortalized mammary epithelial cells (MCF10A) and prostate carcinoma cells (LNCaP) upon USP22 knockdown." (PMID 34007022, 2021).